CCL2 (C-C motif chemokine ligand 2)
Diseases named in the same sentence as CCL2 in open-access papers (continued):
Sharing a sentence is not in itself a finding about the gene and the disease.
tumor (continued). "CCL2 neutralization partially rescued Gata4’s tumor-suppressive phenotype." (PMID 35017504, 2022). "This recognition suggests that the administration of anti-CCL2 treatment may pose the threat of exerting counterproductive effects on tumor metastasis." (PMID 35408440, 2022). "We next tested whether the inhibition of CCL2 synthesis in tumor/stroma coculture altered BM cell migration." (PMID 34874922, 2022). "From this we could postulate that CCL17, CXCL1 and CCL2 act early and in a similar way to indirectly help tumour growth, possibly by upregulating CXCL10 production and myeloid cell expansion, which act more directly on tumour growth." (PMID 35226704, 2022). "It is known that CCL2 is a driver factor for macrophage recruitment in the tumor microenvironment." (PMID 35785026, 2022). "The maintenance of metastatic MB cell stemness by tumor-associated astrocyte-secreted CCL2 is controlled via the JAK2/STAT3-mediated activation of Notch signaling." (PMID 36291792, 2022). "CCL2 could directly bind to tumor-derived exosomes through the glycosaminoglycan side chains of proteoglycans." (PMID 36430471, 2022). "In addition, blocking the recruitment of monocytes to the tumor by targeting the CC-chemokine ligand 2 (CCL2)–CC-chemokine receptor, showed a reduction in tumor growth and less metastasis in a mouse model of PC." (PMID 36106025, 2022). "CCL2 can recruit the macrophage to infiltrate and engulf these senescent tumor cells." (PMID 35915657, 2022). "Furthermore, CCL2 secreted by TAMs targets tumor cells, directly promotes proliferation and metastasis and mediates drug resistance in tumor cells." (PMID 36403055, 2022). "CCL2, as a chemotactic cytokine, can recruit immune monocytes to promote tumor progression." (PMID 36403055, 2022). "Functionally, TAMs promote tumor growth and metastasis by impairing the anti-tumor immune response, among others, by producing chemokines such as C–C motif chemokine ligand 2 (CCL2)." (PMID 35562953, 2022). "However, the CCL2-induced elevation of GC tumor volume and weight was greatly decreased with anti-CD40 mAb or CD40 ×HER2 bsAb treatment." (PMID 35851310, 2022). "It has been suggested that CCL2 might act as an autocrine or paracrine chemokine to promote the growth of tumor cells, which can be partially abolished by CCR2 antagonists or PI3K inhibitors." (PMID 35702353, 2022). "TXA2 signalling was also shown to activate the endothelium, promoting tumour cell survival by mediating the recruitment of pro-metastatic monocytes in proximity to tumour cells through the release of the chemotactic factors CCL2/MCP-1 and CCL5." (PMID 36558983, 2022). "CXCL2 has also been demonstrated to recruit MDSCs and promote tumor growth in breast cancer, pancreatic ductal adenocarcinoma, oral cancer, and glioblastoma, whereas knockdown of CXCR2 in MDSCs and knockdown of CCL2 reduced the recruitment of MDSCs to tumor sites in mice." (PMID 35854339, 2022). "Distinct from the naïve condition, cells from the tumor-bearing animal migrate to CCL2 with a slightly higher potency as compared to CCL7 and achieve near-maximum migration to both ligands at as low as 3ng/mL of recombinant protein plated in the bottom chamber." (PMID 36685592, 2022). "Further, CCL2 affects TAM activity in many ways that affect tumor behavior." (PMID 35053602, 2022). "Furthermore, depleting or downregulating M2-TAMs suppressed tumor growth by inactivating CCL2 and/or CCR2 signaling." (PMID 36303162, 2022). "Thus, the administration of HDACi SAHA in melanoma-bearing mice diminished the CCL2-driven accumulation of host MDSCs at tumor site, allowing effective generation of an antitumor immune response." (PMID 35409020, 2022). "NF-kB-mediated factors like IL-6 and CCL2 prevent tumor cell apoptosis." (PMID 36246629, 2022).
tumor (continued). "Mechanically, the absence of PTEN in tumor cells enhances the level of immunosuppressive cytokines, including CCL2 and VEGF, causing less T-cell infiltration and inhibiting autophagy as well, thereby impairing CTL-mediated cell killing." (PMID 36189283, 2022). "CCL2 also appears to have a vicious role in the tumor microenvironment." (PMID 36685497, 2022). "Moreover, we examined the phenotype of the macrophages and the expression of CCL2 in EZH2 inhibitor-treated 4T1 tumor tissues by IHC." (PMID 36038549, 2022). "GBM cells express high levels of CCL2, which recruits GAMs and promotes tumor growth." (PMID 35448036, 2022). "Moreover, knocking down CCR2 abrogated PCa invasiveness to the bone, whereas, in an in vivo model of PCa metastasis, inhibiting CCL2 activity with neutralizing antibodies decreased the overall tumor burden." (PMID 35406450, 2022). "KLF15 inhibits tumor behaviors, and downregulates CCL2 and CCL7, we were eager to find out whether the downregulation of CCL2 and CCL7 had effects on KLF15-mediated proliferation, migration and invasion suppression." (PMID 36347994, 2022). "A subpopulation of CCR2 (receptor for chemokine CCL2) expressing monocytes was recruited by metastatic tumor cells which enhanced the subsequent extravasation of the tumor cells through the targeted delivery of molecules such as vascular endothelial growth factor(VEGF)." (PMID 35962400, 2022). "CCL2 may contribute to tumor progression and the spread of metastasis and could therefore be an interesting target for anti-cancer drugs." (PMID 33540898, 2021). "However, when treated with a low dose of cisplatin, tumor formation was apparently reduced in clones transduced with CCL2." (PMID 34833360, 2021). "Immunostaining of immune cells in CCL2 KD tumors revealed a striking reduction of CD45+ cells in viable tumor areas, most of which were F4/80+ macrophages, thus correlating the loss of tumor macrophages with inhibition of tumor growth." (PMID 34824220, 2021). "In recent years, CAFs were identified as an important source of CCL2, suggesting that they may regulate tumor immunity in an inflammation-dependent manner." (PMID 34386431, 2021). "The most common chemokines that attract macrophages to the tumor are CCL2, CCL20, CCL5, and CXCL12." (PMID 33919517, 2021). "Further, inhibition of CCL2 signaling was shown to reduce cancer cell metastasis in tumor bearing mice, so CCL2 might be a potential target for the cancer treatment." (PMID 34639088, 2021). "In B-lymphoma cells, the mutation or knockdown of CREBBP or EP300 inhibited H3K27 acetylation, downregulated FBXW7 expression, activated the NOTCH pathway, and downstream CCL2/CSF1 expression, resulting in tumor-associated macrophage polarization to M2 phenotype and tumor cell proliferation." (PMID 33431788, 2021). "Emerging results indicate a considerable concentration of CCL2 in tumor tissue, suggesting that the presence of CCL2 may contribute to tumor spreading and pre-metastatic niche formation." (PMID 34386431, 2021). "After neoplasia occurs, more bone marrow-derived monocytes from the blood vessels are recruited to the site of the tumor, where they secrete growth factors and chemokines such as CCL2, CCL5, vascular endothelial growth factor (VEGF), and transforming growth factor beta (TGF-β)." (PMID 34445193, 2021). "Intriguingly, in a hypoxic environment, CCL2 induced by tumour cells may inhibit the maturation of natural killer cells in PMN and reduce the ability of NK cells to eliminate incoming CTCs, accelerating the homing of cancer cells." (PMID 34464477, 2021). "Expression of CCR2 and CCL2 by human tumor lines and patient samples." (PMID 34804061, 2021). "Molecules such as integrins VLA-4, CD106, the cytokine receptor CCL2 and galactin-1, engaged in the process of MSCs extravasation, could take part in the interplay between MSCs and tumor cells in VITVO50." (PMID 35111750, 2021).
tumor (continued). "However, it is important to note that discontinuing CCL2 inhibition exacerbates tumour metastasis, suggesting the need to develop new therapies to achieve long‐lasting CCL2 inhibition." (PMID 34464477, 2021). "Indeed, the nitration of the inflammatory chemokine CCL2 within the tumor microenvironment (TME) altered its chemoattractant properties finally limiting T cell entry into the primary tumor lesion." (PMID 34675917, 2021). "We have also observed an increase in the concentration of monocyte chemotactic protein-1 (MCP-1/CCL2) at day -7 and -28 in the plasma of mice that bore a tumour induced by injection of HT29-Snail17 cells as compared to control mice injected with HT29-pcDNA cells." (PMID 33419021, 2021). "Moreover, a sub-population of FAP-α expressing CAFs was shown to promote tumor growth by secretion of CCL2 and subsequent recruitment of MDSCs in murine models of hepatic cancer, liver, and lung squamous cell carcinoma." (PMID 34663337, 2021). "The main mechanism of the proangiogenic properties of CCL2/MCP-1 is the recruitment of monocytes into the tumor niche, which are transformed into TAM, which secrete VEGF-A but also other proangiogenic factors such as matrix metalloproteinase 9 (MMP-9) and PGE2." (PMID 34639040, 2021). "Based on the finding that CCL2 inhibition limits tumour angiogenesis, we presume that CCL2 may be a potential anti‐angiogenesis target in cancer therapy." (PMID 34464477, 2021). "At the same time, tumor cells release chemoattractant proteins that recruit TAMs, such as CCL2, CSF-1, granulocyte–macrophage colony stimulating factor (GM-CSF), hepatocyte growth factor or scatter factor (HGF/SF), stroma-derived factor 1 (SDF-1), and glial cell-derived neurotrophic factor (GDNF)." (PMID 33766119, 2021). "Looking into detail in each of these categories, genes previously related to bone tropism were found to be overexpressed in PC3-BM cells, such as CXCR4 and its ligand CSF1, as well as CCL2, all of them directly involved in signaling pathways regulating circulating tumor cells (CTCs) homing to bone." (PMID 34944822, 2021). "However, suppression of CCL2 expression only leads to a transient reduction in myeloid cell recruitment and a temporary delay in metastatic tumor growth in a mouse model of CRC." (PMID 34583750, 2021). "CCL2 KD led to a striking inhibition of tumor growth, as determined by bioluminescent imaging." (PMID 34824220, 2021). "CCL2 and IL-8 have been also shown to induce tumor cell proliferation and EMT, respectively." (PMID 34067929, 2021). "Interestingly, TAMs are mobilized to the peripheral blood and then recruited in the PMNs by many tumor-secreted cytokines and growth factors (e.g., CCL2, CSF-1, VEGF, PLGF, TNF-α, TGF-β), tissue inhibitor of metallopeptidase (TIMP)-1, and exosomes." (PMID 33916915, 2021). "Tumor-derived microRNA-375 was found to mediate tumor cell–macrophage interplay via CCL2; specifically, microRNA-375 could promote CCL2 production in tumor cells and induce macrophage migration." (PMID 34386431, 2021). "A significant positive correlation was found between the expression of FAP, pSTAT3, and CCL2 in the tumor stroma in patients with intrahepatic cholangiosarcoma, a highly aggressive primary desmoplastic tumor associated with poor overall survival and a high probability of recurrence." (PMID 34771577, 2021). "TCF4 or CCL2 silencing in the tumor cells prevent CRC liver metastasis in the mouse model." (PMID 34580284, 2021). "Overall, tumor microenvironment contains many factors favoring the development of M2 like TAMs, CCL2/CCR2 signaling axis not only play a major role in recruitment of monocytes/MØs to contribute to functional polarization of MØs but also can directly polarize MØs." (PMID 34804061, 2021).
tumor (continued). "The presence of tumor-infiltrating immune cells, here represented as macrophages characterized by the markers CD68, CD163, and CCL2, was associated with a superior prognosis, and chemotherapy may not add an advantage for prognosis." (PMID 33467469, 2021). "However, Bonapace and colleagues have demonstrated that a discontinuation of anti-CCL2 treatment accelerates tumor development in a breast cancer model." (PMID 34572939, 2021). "One could argue that signals from the TME could induce parallel production of both versican and CCL2 by tumor cells, which signals could synergize in favor of metastasis colonization." (PMID 33718177, 2021). "Tumor levels of CCL2/MCP-1 were lower in old than young stressed mice." (PMID 34604038, 2021). "Administration of C1142 along with anticancer vaccine augmented CD8+ T‐cell numbers and reduced tumour volume, suggesting that combining CCL2 antibody with the vaccine could be a promising tactic for treating cancer." (PMID 34464477, 2021). "Primary tumors exhibited an early onset of tumor necrosis upon CCL2 KD." (PMID 34824220, 2021). "Additionally, RNS induces the nitration of CCL2 chemokines to inhibit antigen-specific cytotoxic T-cell trafficking into the tumor." (PMID 35004667, 2021). "Interestingly, in the CCL2-null H22 tumor model, pathological immunostaining analysis showed a robust infiltration of CCL2 highly expressed macrophage-like cells in the tumor tissues from SE mice." (PMID 34593796, 2021). "Moreover, CCL2 secreted into the tumor microenvironment induced the expression of COX-2 and the release of PGE2 in a FoxO1-dependent manner in macrophages, and then promoted the proliferation of HCC cells." (PMID 33891564, 2021). "More importantly, CCL2 can be produced not only by a variety of activated cells, such as fibroblasts, lymphocytes, and macrophages in tumor microenvironment, but also by a variety of tumor cells." (PMID 33414423, 2021). "Intriguingly, CAFs also foster tumour metastasis by secreting CCL2." (PMID 34464477, 2021). "In addition, TAMs secrete CCL2, which is critical for the recruitment of Tregs and MDSCs to the tumor." (PMID 34503065, 2021). "CCL2 may enhance the phagocytotic ability of tumor-entrained macrophages and initiate the subsequent release of cell-death-related molecules such as RANTES, MIF, CXCL-12, and IFNγ." (PMID 34386431, 2021). "Similarly, naphthofluorescein did not affect the expression levels of CCR2 in macrophages, those of CCL2 in metastatic lungs, and serum of tumour-inoculated mice." (PMID 34621018, 2021). "Because high levels of CCL2 are correlated with increased numbers of TAMs in tumor tissues in many human tumors, we speculated that the recruitment of TAMs by CCL2 is involved in the function of NLRP7 in promoting CRC progression." (PMID 33838681, 2021). "CCL2 is produced by cancer cells, and it attracts MDSCs into the tumor compartment." (PMID 34061898, 2021). "However, there is also evidence demonstrating that CCL2 enhances the anti-tumor capability of specific cell types such as inflammatory monocytes and neutrophils." (PMID 34386431, 2021). "Similarly, a dramatic reduction of CCL2 was also observed in the blood serum or tumor tissues of CCl4-induced, and DEN/HFD-induced mouse model housing in the EE condition compared to that in SE." (PMID 34593796, 2021). "Similarly, combined expression of Cxcl1 and Ccl2 in 889-S1 tumour cells substantially counteracted the inhibitory effects of USP12 on the TAM infiltration and their PD-L1 expression as well as on CD31+ cell presence." (PMID 34381028, 2021). "Notably, EE activates peripheral SNS and β-ARs signaling in tumor cells and tumor infiltrated myeloid cells, leading to suppression of CCL2 expression and activation of anti-tumor immunity." (PMID 34593796, 2021). "Either blockade of CCL2/CCR2 or β-AR signaling in EE mice lose the tumor protection capability." (PMID 34593796, 2021).
tumor (continued). "In addition, blockade of β-ARs signaling (PROP + SR, blocking all β-ARs) dramatically abrogated the EE-induced CCL2 reduction in the blood and tumor tissue in DEN + CCl4-induced HCC model." (PMID 34593796, 2021). "Two families of chemokines—CC (CCL-2, 3, 5) and CXC (CXCL-1, 2, 5, 6, 8)—employ CCR-2 with monocytes and CXCR-2+ with neutrophils, at the tumour spot which distinguishes between TAMs and tumour-associated neutrophils (TANs), wielding either pro- or antitumour response." (PMID 34336101, 2021). "In the malignant microenvironment, CCL2 crosstalk with C‐C motif chemokine receptor 2 (CCR2) to modulate chemotaxis of monocytes, notably tumor‐associated monocytes, which consequently lead to the modeling of the immune microenvironment and promote cancer progression." (PMID 34525267, 2021). "TANs are recruited in response to CCL2 secreted by tumor cells and stromal cells in the tumor environment and may automatically secrete CCL2 to amplify the inflammation response." (PMID 34386431, 2021). "CCL2 secreted by tumor cells is critical for the killing capacity of neutrophils." (PMID 34386431, 2021). "CCL2 secreted by CRC cells promoted the polarization of pro-tumor M2-like macrophages." (PMID 33838681, 2021). "The presence of tumor-infiltrating immune cells, characterized by the markers CD68, CD163, and CCL2, was associated with a superior prognosis, and chemotherapy may not add an advantage for prognosis." (PMID 33467469, 2021). "In our study, the expression of CCR2 was positively correlated with patients’ survival which indicated that CCL2/CCR2 axis may play anti-tumor effects in LUAD." (PMID 34187403, 2021). "CCL2 may also be an important therapeutic target because it acts directly on tumor cells to promote tumor growth, progression, and resistance to chemotherapy." (PMID 35008577, 2021). "As a result, anti-CCL2 therapy increased the survival time of tumor-bearing mice." (PMID 34025641, 2021). "Biglycan has been demonstrated to trigger the synthesis of the macrophage chemoattractants chemokine (C-C motif) ligand CCL2 and CCL5; thus, it may be possible that biglycan deficiency modulates tumor vasculature through recruitment of macrophages." (PMID 33966638, 2021). "Tumor-derived EVs can bind to soluble secreted cytokines and chemokines (i.e., CCL2 and IL-6) in the tumor microenvironment through their surface-expressed glycosaminoglycan (GAG) side chains of proteoglycans, significantly increase their uptake in the liver, spleen, and lung." (PMID 34616741, 2021). "Additionally, in the presence of CCL2 produced by CAFs, TAMs, and tumor cells, cytotoxic TILs acquire a CD4+CD25+ Tregs phenotype, which leads to secretion of the immunosuppressive transforming growth factor-beta (TGF-β) and IL-10." (PMID 33922362, 2021). "This TRAIL-dependent cytokine and chemokine production was observed in different carcinogenic cell types, and an accumulation of tumor-supportive immune cells in the cancer microenvironment has been described in an endogenous TRAIL/TRAIL-R-mediated chemokine (C-C motif) ligand 2 (CCL2) secretion." (PMID 35008212, 2021). "Moreover, estrogen-induced tumor immune tolerance was revealed to be partially abolished by tamoxifen though suppression of FasL expression as well as blockade of cancer-derived CCL-2/CCL-5." (PMID 33413549, 2021). "CCL2 can be a predictive biomarker for patients prognosis and tumour aggressiveness." (PMID 34464477, 2021). "CCL2 is a chemokine that attracts high CCR2-expressing monocytes to the tumor site." (PMID 33919517, 2021). "Additionally, LUAD tumor cells used in a model of pleural carcinomatosis were found to secrete the chemoattractant CCL2 and the protein osteopontin (SPP1) in order to mediate mast cells recruitment and degranulation." (PMID 33494181, 2021).